RNU6-1042P (RNA, U6 small nuclear 1042, pseudogene)
Gene: Small nuclear RNA gene on chromosome 1 (150,701,866 to 150,701,972, forward strand). Ensembl gene ENSG00000206931.
Homologues: Orthologues: chimpanzee U6 (100% identical), macaque U6 (97% identical), mouse Gm54979 (70% identical), rat LOC120093926 (70% identical). Paralogues in human: RNU6-891P (94% identical), RNU6-15P (92% identical), RNU6-10P (91% identical), RNU6-1145P (91% identical), RNU6-166P (91% identical), RNU6-25P (91% identical), RNU6-33P (91% identical), RNU6-38P (91% identical), RNU6-41P (91% identical), RNU6-47P (91% identical), RNU6-698P (91% identical), RNU6-831P (91% identical), and 1287 more.